PCDHGA10 (protocadherin gamma subfamily A, 10)
Description:
Potential calcium-dependent cell-adhesion protein. May be involved in the establishment and maintenance of specific neuronal connections in the brain.
Synonyms: PCDH-gamma-A10
Tractability: Antibody: UniProt places it where antibodies can reach, with medium confidence; UniProt predicts a signal peptide or a membrane-spanning region; its Gene Ontology location is reachable by antibodies, with medium confidence; the Human Protein Atlas places it where antibodies can reach. PROTAC: its protein half-life has been measured.
Gene: Protein-coding gene on chromosome 5 (141,412,987 to 141,512,975, forward strand). Ensembl gene ENSG00000253846.
Subcellular location: Cell membrane
Subcellular location (Human Protein Atlas): Nucleoplasm; Plasma membrane; Cytosol; Vesicles
Gene Ontology:
Molecular function: cell adhesion molecule binding; calcium ion binding
Biological process: cell adhesion; homophilic cell-cell adhesion
Cellular component: plasma membrane; membrane
Genetic constraint (gnomAD): Loss-of-function variants: 40 observed, 61.29 expected, observed/expected ratio (o/e) 0.65, 90% interval 0.51 to 0.85. The upper end of that interval is the gene's LOEUF score, 0.85, which puts it in group 3 of 6, group 1 being the genes least tolerant of losing a copy. Missense variants: 1,100 observed, 1,263.7 expected, observed/expected ratio (o/e) 0.87, 90% interval 0.83 to 0.92. Synonymous variants: 506 observed, 546.72 expected, observed/expected ratio (o/e) 0.93, 90% interval 0.86 to 1.
Homologues: Orthologues: mouse Pcdhga10 (87% identical). Paralogues in human: PCDHGA9 (79% identical), PCDHGA12 (77% identical), PCDHGA8 (77% identical), PCDHGA7 (76% identical), PCDHGA6 (75% identical), PCDHGA2 (75% identical), PCDHGA4 (75% identical), PCDHGA11 (75% identical), PCDHGA3 (75% identical), PCDHGA1 (75% identical), PCDHGA5 (74% identical), PCDHGB1 (51% identical), and 49 more.
Diseases named in the same sentence as PCDHGA10 in open-access papers:
PCDHGA10 is named in the same sentence as 10 diseases in open-access papers, as found by Europe PMC text mining. Sharing a sentence is not in itself a finding about the gene and the disease. The quoted sentences say what the papers report.
lung squamous cell carcinoma (2 papers, 2024). "PCDHGA10 is significantly upregulated in lung squamous cell carcinoma (LUSC) and a high level of PCDHGA10 expression is associated with a poorer prognosis." (PMID 39208202, 2024). "Recently, it is reported that PCDHGA10 was highly expressed in lung squamous cell carcinoma, and elevated PCDHGA10 levels exhibited a worse prognosis." (PMID 39687617, 2024).
astrocytoma (1 paper, 2024). "PCDHGA10 other mutations (such as c.G1765A, p.G589S; c.A395G/T, D132G/V) have been reported in astrocytoma grade IV." (PMID 39208202, 2024).
bladder cancer (1 paper, 2024). "PCDHGA10 mutation (c.A265G; p.I89V) has not been reported to be associated with gliomas, which has been reported in other tumors (bladder cancer, gastric adenomas, and gastrointestinal stromal tumors)." (PMID 39208202, 2024).
glioma (1 paper, 2024). A benign or malignant brain and spinal cord tumor that arises from glial cells (astrocytes, oligodendrocytes, ependymal cells). "Differential genomic landscapes between LGG and GBM were revealed in the Chinese population, and PCDHGA10, for the first time, was identified as the prognostic factor of gliomas." (PMID 39208202, 2024). "IDH1 is an important biomarker in gliomas, whereas PCDHGA10 mutation has not been reported to correlate with gliomas." (PMID 39208202, 2024). "PCDHGA10 might be a potential biomarker for prognosis in gliomas." (PMID 39208202, 2024). "In addition, PCDHGA10 might be related to the prognosis of GBM, however, additional experiments are required to explore pathologic functions of PCDHGA10 in gliomas." (PMID 39208202, 2024). "However, the potential role of PCDHGA10 in tumorigenesis of gliomas has not been reported." (PMID 39208202, 2024).
tumor (2 papers, 2019 to 2024). "In addition, we found that the expression of PCDHGA10 was related to CD68+ tumor-associated macrophages (TAMs)." (PMID 39687617, 2024). "Here, we aim to explore the correlation between the expression of procalcitonin gamma subfamily A, 10 (PCDHGA10) and clinicopathological characteristics, especially its relation with tumor-infiltrating immune cells (TILs) in GC." (PMID 39687617, 2024). "The present study showed that PCDHGA10 mRNA was considerably more expressed in tumor tissues than in normal tissues using the TCGA datasets." (PMID 39687617, 2024). "As an independent predictor of poor outcome, high expression of PCDHGA10 might orchestrate tumor immunity and might be a potential treatment target for GC." (PMID 39687617, 2024). "Moreover, PCDHGA10 was closely related to tumor immune cell infiltration and immune checkpoints." (PMID 39687617, 2024). "Additional genes that had similar DNA and RNA frequency as DUSP5 and EI24 but no previous research on their potential role as a tumor suppressor were UBXN11, CAPN15, C6orf62, GPRIN1, KIAA2018, PCDHGA10, and PCGF1." (PMID 31484939, 2019).
cancer (1 paper, 2024). A tumor composed of atypical neoplastic, often pleomorphic cells that invade other tissues. "Moreover, it was found that PCDHGA10 expression is associated with clinicopathological features and involved in immune cell infiltration, thus making it a promising target for cancer immunotherapy." (PMID 39687617, 2024).
PCDHGA10 also shares sentences with these, for which no sentence is quoted: gastric adenoma (1 paper); gastric cancer (1); gastrointestinal stromal tumor (1); Sotos syndrome (1).